SHCBP1 (SHC binding and spindle associated 1)
Diseases named in the same sentence as SHCBP1 in open-access papers (continued):
Sharing a sentence is not in itself a finding about the gene and the disease.
cancer (continued). "The SHCBP1 (SHC SH2-domain-binding protein 1) is identified as an important regulator of cancer biology, participating in the modulation of multiple cancer hallmarks." (PMID 41009347, 2025). "From a therapeutic standpoint, genetic or pharmacological inhibition of SHCBP1 through RNAi, CRISPR-mediated editing, or modulation of its upstream regulatory factors has produced strong anti-cancer effects in various preclinical models." (PMID 41009347, 2025). "E2/ERα-SMYD3, SHCBP1, H3K4me3 and Kras-MAPK in all developmental stages of mammary tissues in the Brca1MKO mouse and parous mammary epithelial cells and serve as a cancer driver in general, although a stronger effect is observed in early pregnancy because of the higher levels of E2/ERα signaling." (PMID 40157910, 2025). "To validate the binding of the genes with these four antibodies, we examined 8 candidate genes that are involved in cancer progression, including Esr1, Bcas3, and Bard1, as well as Crebbp, Myc, Rel, Gadd45g, and Shcbp1 (not shown)." (PMID 40157910, 2025). "WEE1 kinase is a key gatekeeper of the G2–M transition through inhibitory phosphorylation of CDK1 at the conserved Tyr15 residues and is an effective anti-cancer target, we subsequently examined the expression of WEE1 kinase protein and mRNA levels after SHCBP1 knockdown in three tumour cell lines." (PMID 38365687, 2024). "The mRNA and protein of the SHCBP1 gene are expressed in proliferating cells, including cancer cells, but are not expressed in stable cells, such as skeletal muscle and cardiomyocytes." (PMID 33291601, 2020). "We also have identified that SHCBP1 may be indispensable for the stem cell-like phenotype driven by EGF-β-catenin signaling and is up-regulated in NSCLC and other cancers in a manner correlated with unfavorable clinical prognosis of the disease." (PMID 30177836, 2019). "Our findings disclose that SHCBP1 is a novel downstream target gene of SS18-SSX1, and demonstrate that the oncogene SS18-SSX1 promotes tumorigenesis by enhancing the levels of SHCBP1, that normally serves as a cancer promoting factor." (PMID 27572315, 2016). "Recent studies indicate that, although SHCBP1 is not a traditional oncogene, it plays a significant role in antagonizing tumor-suppressive mechanisms, ultimately conferring a proliferative benefit to cancer cells." (PMID 41009347, 2025). "LGG was the only cancer type that showed a negative correlation with SHCBP1 expression." (PMID 36920183, 2023). "SHCBP1 mRNA and protein are absent in normal, quiescent tissues but are selectively expressed in tissues containing proliferating cells or even cancer cells, demonstrating that SHCBP1 may be involved in tumor development." (PMID 31007608, 2019). "In addition, SHCBP1 was found to be mainly expressed in the nucleus of cancer cells in NSCLC tissues, regardless of IHC or immunofluorescence staining, which may be related to its functions." (PMID 38365687, 2024). "Thus, our findings have not only revealed previously unknown significance of EGF-stimulated release of SHCBP1 but more importantly also uncovered a new mode of crosstalk between the EGFR and β-catenin pathways and a novel mechanism involved in EGFR regulation of cancer cell stemness." (PMID 30177836, 2019).
tumor (26 papers, 2015 to 2026). "Meanwhile, we also observed similar results in NSCLC cells that express activating mutation-possessed EGFR, as knockdown of SHCBP1 remarkably suppressed tumor sphere formation capacity as well as activation of β-catenin signaling." (PMID 30177836, 2019). "These associations indicate that SHCBP1 may influence the immune landscape of the TME by affecting tumor mutation burden (TMB) and microsatellite instability (MSI) status." (PMID 41009347, 2025). "In addition, as an intracellular signaling protein, SHCBP1 was associated with tumor growth, migration, and invasion via the mediation of several signaling pathways and regulation of the cell cycle, apoptosis, and differentiation." (PMID 36920183, 2023). "To test whether the high expression and dynamic localization of SHCBP1 in M phase was closely associated with its functions in tumour cells, we performed SHCBP1 knockdown in NSCLC (A549 and NCI-H1299) and HeLa cell lines to observe their effects on cell cycle progression." (PMID 38365687, 2024). "Meanwhile, we found that patients bearing lung tumors with a high level of nuclear SHCBP1 had a shorter overall survival time, indicating that nuclear SHCBP1 could be a causative factor for tumor progression and represent a valuable biomarker for the prognosis of NSCLC." (PMID 30177836, 2019). "Experimental studies demonstrated that SHCBP1 knockdown suppressed cell proliferation and tumor growth." (PMID 42187612, 2026). "In vitro and in vivo experiments were then conducted to evaluate the effects of SHCBP1 knockdown on tumor growth." (PMID 42187612, 2026). "Functional assays, including Transwell, cell counting kit-8 (CCK-8), colony assays, and in vivo tumor models, evaluated the effects of Rh7 and SHCBP1 on GC cell behaviors." (PMID 40657397, 2025). "Consistently, the protein levels of Shcbp1, Kras, and pMek were significantly decreased in tumor tissues expressing either sgSmyd3 or sgShcbp1 compared to the parental control tissues." (PMID 40157910, 2025). "We also verified that SHCBP1 knockdown can increase the chemotherapy sensitivity of docetaxel in vivo through subcutaneous tumor formation experiments in nude mice." (PMID 39949984, 2025). "This regulatory flexibility enables SHCBP1 to adapt its function within diverse TMEs and promote tumor aggressiveness." (PMID 41009347, 2025). "PCa bone metastases presented increased SHCBP1 expression, indicating a higher tumor stage and worse prognosis." (PMID 39949984, 2025). "The utilization of an advanced analysis method, WGCNA, further recognized SHCBP1 as one of the prognostic markers, showing a substantial correlation with tumor stage and diminished survival." (PMID 41009347, 2025). "In vivo, Rh7 suppressed tumor size and weight, while SHCBP1 overexpression attenuated these effects." (PMID 40657397, 2025). "Detailed investigation of TCGA datasets indicates that elevated SHCBP1 expression is strongly correlated with advanced clinicopathological characteristics, such as increased tumor size, higher histological grade, and lymph node metastasis." (PMID 41009347, 2025). "The effect of SHCBP1 on dendritic cell maturation impacts tumor immunity and influences sensitivity to immune checkpoint inhibitor (ICI) therapy." (PMID 41009347, 2025). "Inhibition of the CBP/β-catenin complex by ICG-001 diminishes SHCBP1-dependent cell proliferation and tumor expansion." (PMID 41009347, 2025). "This review summarizes SHCBP1’s diverse roles in tumor pathogenesis and outlines future research directions to develop SHCBP1-targeted strategies." (PMID 41009347, 2025). "Collectively, these findings indicate that SHCBP1 contributes to cellular survival not only under basal conditions but also by protecting tumor cells against cytotoxic therapies." (PMID 41009347, 2025). "The tumor volume of mice in the Rh7-treated group was smaller, while the Rh7 + SHCBP1 overexpression group reversed the effect of Rh7 treatment." (PMID 40657397, 2025).
tumor (continued). "Considering the diverse roles of SHCBP1 in tumor progression, therapy resistance, and modulation of the TME, it has been recognized as an attractive therapeutic target." (PMID 41009347, 2025). "SHCBP1 also modulates cytoskeletal organization, a process vital for tumor cell migration and invasion." (PMID 41009347, 2025). "SHCBP1 is known to regulate tumor development by facilitating cell-cycle progression, augmenting cell survival, and mediating signal transduction." (PMID 40799237, 2025). "Loss of SHCBP1 inhibited ESCC cell proliferation and migration through the TGF-β pathway and suppressed tumor growth in mice." (PMID 40657397, 2025). "Combined treatment with SHCBP1 siRNA and autophagy inhibitors reverses cisplatin resistance and decreases tumor burden in vivo." (PMID 41009347, 2025). "Experimental results further revealed high SHCBP1 expression in gastrointestinal cancers, underscoring its potential value in tumor immunotherapy." (PMID 40657397, 2025). "Collectively, these findings demonstrate that SHCBP1 is an important mediator of mitogenic and cell cycle-related signaling, thereby supporting the proliferative potential of tumor cells." (PMID 41009347, 2025). "Preclinical models indicate that genetic depletion or pharmacologic disruption of SHCBP1 limits tumor growth, increases sensitivity to chemotherapy, and reduces metastatic capacity." (PMID 41009347, 2025). "Altogether, targeting SHCBP1 in combination with low-dose DNA-damaging drugs not only attenuated tumour cell cycle checkpoints but also compromised DNA repair, leading to the synergistic effects of the combination strategy." (PMID 38365687, 2024). "SHCBP1 protein was detected mainly in the nucleus of tumour cells, with a small amount present in the cytoplasm." (PMID 38365687, 2024). "Our results provide a preclinical rationale for the role of SHCBP1 in predicting tumour prognosis and as a therapeutic target." (PMID 38365687, 2024). "We observed increased SHCBP1 protein levels in tumour cells with escalating doses of DNA-damaging agents (within a cell-lethal dose) exposure, including etoposide (ETOP), cisplatin (CDDP), and radiation." (PMID 38365687, 2024). "Based on the theory that tumour cell survival during DNA damage largely depends on efficient cell cycle checkpoints, we further demonstrated that the combination of SHCBP1 inhibition and low-dose DNA-damaging drugs had synergistic effects on tumouor therapy." (PMID 38365687, 2024). "Then, we detected the percentage of PHH3-positive M-phase tumour cells after SHCBP1 knockdown combined with low-dose ETOP or CDDP treatment by immunostaining assay, flow cytometry, and western blotting analysis." (PMID 38365687, 2024). "Western blotting and qRT-qPCR analyses showed higher SHCBP1 expression in tumour tissues than in adjacent normal tissues (ANTs), with most ANTs hardly expressing SHCBP1." (PMID 38365687, 2024). "The expression of SHCBP1 in mouse subcutaneous tumour tissues was also detected by western blot analysis throughout the modeling period." (PMID 38365687, 2024). "Consistently, patients with low SHCBP1 expression in tumour tissue were more sensitive to radiotherapy." (PMID 38365687, 2024). "SHCBP1 expression, quantified by the immunohistochemical (IHC) scoring, was also significantly correlated with patient tumour stages and ki67 index (p < 0.05)." (PMID 38365687, 2024). "Based on these findings, SHCBP1 knockdown in combination with low-dose DNA-damaging agents had synergistic tumouricidal effects on tumour cells." (PMID 38365687, 2024). "In our study, targeting SHCBP1 showed a consistent strong inhibitory effect on tumour progression both in vitro and in vivo, likely mainly through WEE1 kinase downregulation." (PMID 38365687, 2024). "A member of the neural precursor cell proliferation process, SHCBP1 is reported to promote tumor cell signaling and proliferation." (PMID 38896472, 2024).
tumor (continued). "So far, little is known about the role of SHCBP1 in the tumor immune microenvironment, which is worthy of further investigation." (PMID 36920183, 2023). "SHCBP1 is involved in various cell signalling processes, cell proliferation, and upregulated in various neoplasms." (PMID 37018234, 2023). "The TMB, MSI, and tumor microenvironment analysis indicated that SHCBP1 was closely related to immune checkpoints, immune targets, as well as CD4+ naive T cell, CD8+ T cell, and neutrophil." (PMID 36920183, 2023). "In this study, we analyzed the expression of SHCBP1 in 33 tumor types, and SHCBP1 expression was elevated in most of these types except for PAAD, AML, LGG, SARC, and TGCT when compared with the corresponding normal tissues." (PMID 36920183, 2023). "Resveratrol further downregulates the phosphorylation level of ERK1/2 by inhibiting SHCBP1 expression, thus inhibiting tumor cell proliferation." (PMID 38005336, 2023). "We investigated SHCBP1 expression, prognosis, genetic alterations, tumor mutational burden (TMB) score, microsatellite instability (MSI) and tumor microenvironment from TIMER2, GEPIA2, UALCAN and cBioPortal databases." (PMID 36920183, 2023). "In general, SHCBP1 can promote tumor growth and invasion in GC by regulating the CDK4-cyclin D1 cascade and caspase-3 and caspase-PARP-dependent apoptosis pathways." (PMID 36920183, 2023). "Data from GEPIA also showed that the expression of SHCBP1 in tumor tissues was higher than that in normal tissues." (PMID 35013128, 2022). "Matrigel-coated Transwell chambers were used to detect the effect of SHCBP1 depletion on tumor cell invasion." (PMID 35013128, 2022). "As predicted by the in vitro studies, we found that trastuzumab treatment moderately slowed tumor growth with shCtrl cells, while significantly reduced tumor growth in SHCBP1-depleted cell xenograft models." (PMID 33990570, 2021). "By contrast, at least 5 × 104 vector-control A549 cells were needed to form a tumor, altogether indicating that high-level SHCBP1 is able to promote NSCLC cell stemness and tumorigenesis." (PMID 30177836, 2019). "By using nuclear extraction and western blot assay, we detected far more nuclear SHCBP1 in NSCLC tumor tissues as compared with that in the corresponding adjacent non-cancerous lung tissues." (PMID 30177836, 2019). "The tumor size at the time of death in the SHCBP1-siRNA lentivirus group was 413 ± 69.6 mm3, which was significantly smaller than in the NC-siRNA group (1165 ± 160.3 mm3)." (PMID 27572315, 2016). "In this investigation, we found that SHCBP1 affects tumor cell EMT; hence, its modulation of PLK1 activation may also affect EMT." (PMID 39949984, 2025). "Notably, high SHCBP1 levels often coincide with more aggressive tumor characteristics and poorer prognosis." (PMID 41009347, 2025). "The positive correlation was also observed between the expression of Smyd3 and Shcbp1 in premalignant virgin MG, P12 mammary and tumor tissues at both protein and mRNA levels, indicating Shcbp1 might mediate Smyd3 signaling." (PMID 40157910, 2025). "High SHCBP1 expression indicated a higher tumor stage and worse survival." (PMID 39949984, 2025). "Taken together, these observations indicate that SHCBP1 may serves not only as a surrogate marker for tumor aggressiveness, but also as an integrative indicator of molecular subtype, immune evasion, and therapeutic response." (PMID 41009347, 2025). "Trametinib, a potent inhibitor of MEK/MAPK, could reverse the expression of Smyd3 and Shcbp1 in both Brca1 mutant and WT tumor bearing mice." (PMID 40157910, 2025). "To further confirm whether the inhibitory effect is indeed due to the inhibition of Smyd3 or Shcbp1, we orthotopically implanted G600 cells stably expressing either sgSmyd3 or sgShcbp1 into the fat pad of nude mice and monitored tumor growth." (PMID 40157910, 2025).
tumor (continued). "Altogether, these findings indicate that SHCBP1 may support the persistence of stem-like, therapy-resistant populations, facilitating sustained tumor growth and recurrence." (PMID 41009347, 2025). "Our data highlights the crucial role of SHCBP1 in clinical outcomes and tumor progression in TNBC." (PMID 40799237, 2025). "High SHCBP1 expression is linked to greater infiltration of tumor-associated macrophage (TAM), CD4+ naïve T cells, CD8+ T cells, and neutrophils, as well as elevated levels of immune checkpoint proteins, including PD-L1 and TGFBR1 in multiple tumor types." (PMID 41009347, 2025). "Recent studies have highlighted the important function of SHCBP1 in tumor progression." (PMID 40657397, 2025). "To determine the reasons for the multipolar spindle formation and subsequent suppression of the metaphase-anaphase transition in tumour mitotic cells after SHCBP1 inhibition, we screened a series of centrosome and spindle assembly checkpoint (SAC) related proteins (data not shown)." (PMID 38365687, 2024). "The DNA-damaging agent ETOP induced G2 arrest in tumour cells, while SHCBP1 inhibition prompted cells with unrepaired DNA damage to override this arrest and enter the M phase, which may trigger the onset of mitotic catastrophe and lead to cell death." (PMID 38365687, 2024). "Moreover, both in vivo and in vitro experiments confirmed the significant inhibitory effects of SHCBP1 knockdown on tumour growth." (PMID 38365687, 2024). "Moreover, SHCBP1 inhibition in tumour cells abrogated the G2–M checkpoint by downregulating the WEE1 kinase to break the balance between genotoxic stress and the cell cycle arrest and repair system, resulting in further tumour growth inhibition." (PMID 38365687, 2024). "In this paper, we found that the nucleoprotein SHCBP1 exhibits dynamic spatiotemporal expression during the tumour cell cycle, and SHCBP1 knockdown slowed cell cycle progression by inducing spindle disorder, as reflected by premature mitotic entry and multipolar spindle formation." (PMID 38365687, 2024). "Our findings demonstrated the important clinical role of SHCBP1 in tumour progression." (PMID 38365687, 2024). "However, SHCBP1 knockdown combined with tubulin-toxic drugs weakened the killing effect of the drugs on tumour cells, which is an interesting phenomenon that deserves further study." (PMID 38365687, 2024). "In addition, we found that the premature M-phase entry in tumour cells after SHCBP1 knockdown was due to WEE1 kinase downregulation, which resulted in decreased CDK1 phosphorylation at the Tyr15 residue." (PMID 38365687, 2024). "SHCBP1 is not only an effective prognostic indicator but also a potential biological treatment target, which was confirmed in this study of tumour data collected from three different clinical sources (TCGA database, Union Hospital clinical sample, and out-of-hospital tissue array)." (PMID 38365687, 2024). "SHCBP1 expression was higher in all tumour cells than in immortalized HBE and 293wt cells." (PMID 38365687, 2024). "SHCBP1 expression was associated with clinical prognosis, genetic alterations, immune checkpoint expression, TMB, MSI, immune cell infiltration, and cellular processes, which provided a forward-looking view for effective tumor diagnosis and treatment." (PMID 36920183, 2023). "As an upstream protein of the ERK1/2 signaling pathway, SHCBP1 may be involved in the process of resveratrol-mediated inhibition of tumor cell proliferation." (PMID 38005336, 2023). "We found that depletion of SHCBP1 remarkably repressed the cellular stemness enhancement caused by EGF stimulation, as revealed by reduced EGF-promoted formation of tumor spheres, expression of stem cell markers, and CD44/EpCAM double-positive as well as SP fraction." (PMID 30177836, 2019).